ARMCX6 (armadillo repeat containing X-linked 6)
Description:
May regulate the dynamics and distribution of mitochondria in neural cells.
Synonyms: FLJ20811; GASP10
Tractability: Antibody: UniProt predicts a signal peptide or a membrane-spanning region. PROTAC: ubiquitination databases record sites on it.
Gene: Protein-coding gene on chromosome X (101,615,118 to 101,618,003, reverse strand). Ensembl gene ENSG00000198960.
Subcellular location: Mitochondrion; Mitochondrion outer membrane
Subcellular location (Human Protein Atlas): Cytosol; Nuclear membrane; Nucleoplasm
Gene Ontology:
Biological process: axonal transport of mitochondrion
Cellular component: cytosol; mitochondrial outer membrane; mitochondrion; axon cytoplasm
Homologues: Orthologues: chimpanzee ARMCX6 (99% identical), macaque ARMCX6 (96% identical), dog ARMCX6 (81% identical), pig ARMCX6 (76% identical), guinea pig ARMCX6 (74% identical), rabbit ARMCX6 (71% identical), mouse Armcx6 (70% identical), rat Armcx6 (69% identical), tropical clawed frog armc10 (23% identical), zebrafish armc10 (21% identical), Caenorhabditis elegans Y67A10A.7 (10% identical). Paralogues in human: ARMCX1 (33% identical), ARMCX2 (33% identical), ARMCX3 (33% identical), ARMC10 (29% identical), ARMCX4 (28% identical), GPRASP2 (22% identical), GPRASP1 (20% identical), ARMCX5 (19% identical), GPRASP3 (16% identical), ARMC12 (15% identical).
Diseases named in the same sentence as ARMCX6 in open-access papers:
ARMCX6 is named in the same sentence as 4 diseases in open-access papers, as found by Europe PMC text mining. Sharing a sentence is not in itself a finding about the gene and the disease. The quoted sentences say what the papers report.
dementia (1 paper, 2021). Loss of intellectual abilities interfering with an individual's social and occupational functions. "The 23rd and 24th ranked genes, ARMCX6 and BRD4, were linked to impairments in cognition and memory, which are regarded as the common symptoms of dementia." (PMID 34492068, 2021).
rheumatoid arthritis (1 paper, 2020). A chronic, systemic autoimmune disorder characterized by inflammation in the synovial membranes and articular surfaces. "Studies have shown that ARMCX5 can be activated by binding to the oncogene ZnF217 and ARMCX6 upexpressed at least 2-fold in peripheral blood monocytes of rheumatoid arthritis patients compared to those identified using oligonucleotide array." (PMID 32685472, 2020).
tumor (1 paper, 2018). "The cluster of upregulated genes contained those mainly involved in metabolism such as GGT1 (gamma glutamyl transferase 1), vesicular traffic/secretion such as SYT13 (synaptotagmin XIII) and tumor suppression such as ARMCX3 (armadillo repeat-containing X-linked protein 3) and ARMCX6." (PMID 30337535, 2018).
ARMCX6 also shares sentences with these, for which no sentence is quoted: gastric tumors (1 paper).